RN7SL580P (RNA, 7SL, cytoplasmic 580, pseudogene)
Gene: Miscellaneous RNA gene on chromosome 6 (51,975,673 to 51,975,959, forward strand). Ensembl gene ENSG00000240641.
Homologues: Orthologues: chimpanzee Metazoa_SRP (99% identical), macaque Metazoa_SRP (86% identical). Paralogues in human: RN7SL1 (79% identical), RN7SL2 (78% identical), RN7SL3 (77% identical), RN7SL709P (77% identical), RN7SL395P (76% identical), RN7SL823P (76% identical), RN7SL587P (76% identical), RN7SL630P (76% identical), RN7SL122P (75% identical), RN7SL378P (75% identical), RN7SL581P (75% identical), RN7SL126P (75% identical), and 703 more.